MPO (myeloperoxidase)
Diseases named in the same sentence as MPO in open-access papers (continued):
Sharing a sentence is not in itself a finding about the gene and the disease.
fungal infections (23 papers, 2010 to 2025). "According to previous studies, severe MPO deficit is primarily associated with recurring fungal infections and critical function of NETs has been proven in combating pathogens, including fungal hyphae, that are too big to be eliminated intracellularly." (PMID 38912350, 2024). "MPO-deficient neutrophils perform the function of phagocytosis, but require the activity of the MPO enzyme when it comes to fungal infections." (PMID 36982799, 2023). "In humans, it can lead to severe recurrent fungal infections if MPO is deficient, as demonstrated in mice, where MPO has been found to play an important role against large pathogens such as mycelia." (PMID 37373412, 2023). "Severe MPO deficiency is associated with a higher incidence of bacterial and fungal infections; however, the majority of MPO deficiency cases are thought to be subclinical." (PMID 36421487, 2022). "She showed recurrent fungal infections that may be at least partially attributable to myeloperoxidase deficiency." (PMID 37198333, 2023). "The identified pathogenic MPO variants are a known cause of myeloperoxidase deficiency and may contribute to the recurrent fungal infections." (PMID 37198333, 2023). "Patients with complete MPO-deficiencies are prone to recurrent mucosal fungal infections, but their immune deficiency is milder than chronic granulomatous disease (CGD) which is associated with mutations that disrupt the production of the upstream oxidant superoxide by the NADPH oxidase Nox2." (PMID 35945238, 2022). "This phenomenon explains the rare but severe episodes of systemic fungal infection in patients with complete MPO deficiency and is consistent with one of our MPO-deficient patients being misdiagnosed with CGD in the acute phase of infection due to the lack of superoxide production." (PMID 35945238, 2022). "In this case, the presence of kidney transplantation under immunosuppressive therapy and diabetes mellitus may have been the triggering factors for the acquired MPO deficiency and the subsequent invasive fungal infection." (PMID 35845289, 2021). "Moreover, in cases of fungal infection it has been shown that microbe clearance by MPO-deficient cells is much less efficient than that of normal neutrophils." (PMID 32661559, 2021). "Epidemiological studies associate myeloperoxidase-deficiency with increased risk of fungal infection, myeloperoxidase-deficient mice are vulnerable to Candida infection, and myeloperoxidase-deficient neutrophils display reduced ability to produce fungicidal neutrophil extracellular traps (NETs)." (PMID 29883484, 2018). "In this context, our previous investigation of pulmonary immune response to fungal infection in DA and AO rats revealed lower intracellular MPO activity in AO rats." (PMID 40177400, 2025). "Myeloperoxidase (MPO), a lysosomal protein, functions in response to pathogens during bacterial and fungal infections and contributes to pathogen clearance within the phagosome." (PMID 38322992, 2024). "Hence, higher MPO enzymatic activity can be expected when the body is challenged with an acute bacterial infection or fungal infection, which is often used as a biomarker for acute infections in humans." (PMID 41514704, 2025). "Together, one might conclude that action of MPO in innate host defense might be essential only in case of serious fungal infections and/or in situations where exposure of pathogens overwhelms the capacity of other host defense mechanisms." (PMID 32661559, 2021). "In fact, defensins have been shown to be extremely cytotoxic towards C. neoformans and mice lacking MPO are hyper-susceptible to C. neoformans and other fungal infections." (PMID 21203393, 2010). "In addition to macrophages, neutrophils are known to partially use the myeloperoxidase enzyme to eliminate fungal infections, and may provide an interesting approach for the diagnosis of T. marneffei infection." (PMID 37367583, 2023).
fungal infections (continued). "However, the presence of myeloperoxidase in spontaneously released extracellular vesicles and the lack of susceptibility of patients lacking myeloperoxidase to fungal infections hint that other factors are also involved." (PMID 34986319, 2022). "In contrast, many patients with loss of function mutations of MPO might have no obvious clinical symptoms or show an increased predisposition only toward fungal infections (caused mainly by Candida albicans)." (PMID 30891045, 2019). "It is of importance to note that unlike chronic granulomatous disease patients who are deficient in the gp91 component of the NOX2 complex and susceptible to recurrent bacterial and fungal infections, patients with MPO deficiency generally do not exhibit an increased frequency of infections." (PMID 29780806, 2018). "When NET formation is impaired, as a result of NADPH oxidase or myeloperoxidase (MPO) deficiency, an immunodeficiency condition ensues, i.e., in chronic granulomatous disease, due to defective NADPH oxidase, restoration of NET formation by gene therapy allowed the control of severe fungal infection." (PMID 27895639, 2016). "Laboratory studies repeated 3 months after controlling the fungal infection no longer showed cytological abnormalities, and FCM revealed a normal SSC/FSC distribution and a partial recovery of the MPO deficiency, both in neutrophils and monocytes (30% and 38% of the normal, respectively)." (PMID 35845289, 2021).
Hyperglycemia (23 papers, 2013 to 2026). An increased concentration of glucose in the blood. "Both hyperglycemia and LPS exposure are associated with heightened level of myeloperoxidase activity." (PMID 40098957, 2025). "In a diabetic state, MPO activation gives rise to an upsurge in the production of oxidants which exert cytotoxic and oxidative activity; lingering hyperglycemia is commonly linked with elevated levels of an activated MPO enzyme." (PMID 32148647, 2020). "This phenomenon could underlie the downregulation of bactericidal activity of MPO and neutrophils, and hence of innate immunity, giving rise to wound healing impairment and susceptibility to infection in patients with hyperglycemia." (PMID 36421449, 2022). "• Hyperglycemia causes greater PMN infiltration but low MPO activities in the lung tissue." (PMID 23622115, 2013). "At 170 mg/kg bw, ATR reduced hyperglycemia by 66% and attenuated seminal inflammation, decreasing leukocyte infiltration (-51%) and myeloperoxidase (MPO) activity (-68%)." (PMID 41828633, 2026). "Concurrently, hyperglycemia upregulates myeloperoxidase (MPO) activity, further exacerbating ROS accumulation and oxidative stress, which is closely associated with vascular endothelial dysfunction." (PMID 40385356, 2025). "It has been reported that hyperglycaemia inhibits phagocyte microbicide activity as it decreases phagocyte opsonization, reduces the granular content in neutrophils, and alters myeloperoxidase production." (PMID 30705678, 2018). "The myeloperoxidase assay further confirmed that the enzymatic activity of activated mononuclear cells was enhanced in the gastric wall of rats with chronic hyperglycemia." (PMID 29095895, 2017). "Hyperglycemia can stimulate the production of hydrogen peroxide, resulting in an increase of MPO activity." (PMID 26451069, 2015). "Hyperglycemia induces neutrophil dysfunction by modulating one of the neutrophil biochemical pathways, myeloperoxidase (MPO)." (PMID 24899891, 2014). "Collectively, these data suggest that the conditions mimicking hyperglycemia and the serum environment of patients with T2DKD promote key features associated with NET formation in neutrophils, as evidenced by the characteristic MPO release pattern." (PMID 40862112, 2025). "When we treated NOD mice with inhibitors of myeloperoxidase and neutrophil elastase, two key effectors of activated neutrophil activity, alone or in combination, we were unable to prevent the progression to hyperglycemia in any manner different from untreated control mice." (PMID 33776903, 2021). "It is speculated that neutrophils which contains MPO is recruited by hyperglycemia to adipose cells or β-cells to form singlet oxygen." (PMID 23691063, 2013). "Therefore, we speculate that neutrophils containing myeloperoxidase are recruited by hyperglycemia to adipose cells or β-cells, which results in the formation of singlet oxygen." (PMID 26132231, 2015). "Even though hyperglycemia promoted the mRNA expression of IL-8 or TLR4 and PMN aggregation, it diminished the MPO activity in the lung tissue." (PMID 23622115, 2013). "We speculated that the relationship between MPO and CAD may be stronger on a background of hyperglycemia." (PMID 26451069, 2015).
melanoma (23 papers, 2011 to 2026). A malignant, usually aggressive tumor composed of atypical, neoplastic melanocytes. "We confirmed the appearance of NETs in melanoma cell–neutrophil cocultures by fluorescence staining of markers associated with NETs, including chromatin, MPO and citrullinated histone 3 (H3Cit), and performed experiments interfering with neutrophil-associated protease activity and NETs." (PMID 38730718, 2024). "Interestingly, the leakage of dextran was significantly faster from B16F10 tumors in MPO−/− animals compared to MPO+/+ animals suggesting that the vasculature was more permeable in melanoma tumors grown in MPO-deficient environments." (PMID 33652682, 2021). "In addition, MPO on NETs showed cytotoxicity to melanoma cells, causing necrosis." (PMID 40239243, 2025). "Knockout or pharmacologic inhibition of MPO accelerates melanoma growth, underscoring the significance of MPO-dependent HOCl flux in restraining tumor progression." (PMID 41462936, 2025). "We observed a slight increase in the number of myeloperoxidase‐positive neutrophils in melanomas from aged patients, in contrast to melanomas from young patients." (PMID 41258756, 2025). "Several studies have shown that elevated levels of MPO, MMP-9 and IL-8 are associated with poor prognosis and compromised immune response in melanoma." (PMID 38730718, 2024). "In another study, both genetic and pharmacological blockades of MPO increased the success of immune checkpoint therapy in experimental models with primary melanoma." (PMID 38201509, 2023). "In melanoma, MPO is a representative component of NETs, which can kill melanoma cells (cell line A375) and decline the ability of proliferation and metastasis after implementation." (PMID 36384979, 2022). "In contrast, MPO-derived HOCl has been suggested to protect against tumorigenesis by inhibition of NF-κβ and as such, MPO inhibition or in MPO KO mice melanoma growth was augmented." (PMID 36293108, 2022). "NF-κB transcriptional activation within melanoma tumors were compared in wild type (MPO+/+) and syngeneic MPO-deficient (MPO−/−) animals with skin window chambers." (PMID 33652682, 2021). "Granules contain components involved in killing target melanoma cells either directly (hydrolases, defensins) or indirectly (myeloperoxidase dependent HClO formation connected with oxidative burst)." (PMID 27927165, 2016). "Exploring the relevance of NET formation in melanoma-cell–neutrophil cocultures, we can confirm the presence of NETs in nonadherent cocultures by the visualization of citrullinated histone H3 (H3cit), MPO and DNA (via Hoechst) both in untreated and treated conditions with dual-targeted therapy." (PMID 38730718, 2024). "We could show that while advanced-melanoma patients responding to targeted therapy were characterized by higher pretreatment MPO levels, the pretreatment MMP-9, HGF and IL-8 levels were similar in both responders and nonresponders." (PMID 38730718, 2024). "Moreover, melanoma cells upregulate the pro-inflammatory activities of neutrophils as well as the expression of tumor-promoting factors, such as MPO, MMP-9 and NETs." (PMID 37525065, 2023). "There was a significant increase in MPO in melanoma tissue arrays." (PMID 38201509, 2023). "MPO was shown to kill B-16 melanoma cells and inhibit their growth in mice after implantation." (PMID 23508552, 2013). "The 12 CpG loci identified by PAM analysis that provided the most accurate prediction of melanoma were RUNX3_P393_R, RUNX3_P247_F, RUNX3_E27_R, COL1A2_E299_F, MPO_P883_R, TNFSF8_E258_R, CD2_P68_F, EVI2A_P94_R, OSM_P188_F, ITK_P114_F, FRZB_P406_F, and ITK_E166_R." (PMID 21375697, 2011). "Notably, cancers such as melanoma, AML, and ovarian cancer harbor uniquely expressed genes, including well-characterized immunotherapy targets like PRAME, MPO and MUC16." (PMID 40672284, 2025).
melanoma (continued). "Additionally, MPO has been shown to promote migration and invasion of human choriocarcinoma JEG-3 cells., and inhibiting MPO can enhance the efficacy of melanoma immunotherapy." (PMID 40547041, 2025). "MPO directly showed activation of PMN by binding to the CD11b receptor, while HOCl triggered inhibition of NF-κB and subsequent CCR2 expression in keratinocytes and melanoma cells." (PMID 38736886, 2024). "Finally, in a cohort of stage IV melanoma patients, we found increased circulating levels of neutrophil-related mediators, such as MMP-9, MPO, GM-CSF and CXCL8/IL-8, as well as increased levels of NET biomarkers, compared to healthy controls." (PMID 37525065, 2023). "In addition, serum levels of myeloperoxidase, matrix metalloprotease-9, CXCL8/IL-8, granulocyte and monocyte colony-stimulating factor and NETs were significantly increased in patients with advanced melanoma compared to healthy controls." (PMID 37525065, 2023). "We demonstrated that melanoma CM, but not primary melanocyte CM, were able to induce the PMN release of MPO and MMP-9, known angiogenic and pro-tumorigenic factors." (PMID 37525065, 2023).
renal failure (23 papers, 2001 to 2025). "MPO-ANCA seropositive participants had a higher probability of being in kidney failure (KDIGO stage 5) at diagnosis than PR3-ANCA seropositive participants (0.36 (95% CI 0.23 to 0.52) vs 0.09 (95% CI 0.05 to 0.15))." (PMID 38886004, 2024). "In this report, we present a case of a 69-year-old female who presented with advanced renal insufficiency and evidence of pulmonary hemorrhage and was MPO-ANCA-positive with a clinical phenotype of granulomatosis with polyangiitis." (PMID 35645206, 2022). "In this case, ATIN presented as sustained renal insufficiency and high MPO-ANCA titer despite withdrawal of cimetidine." (PMID 34461843, 2021). "In our cohort, we also observed worse kidney function at diagnosis (as indicated by lower eGFR and a higher probability of meeting criteria for KDIGO stage 5, kidney failure) in individuals with MPO-ANCA, with the opposite observed in PR3-ANCA seropositive patients." (PMID 38886004, 2024). "Here, we describe a case of an older woman presenting with ATIN and a high titer of MPO-ANCA while taking cimetidine, who underwent repeated renal biopsy to assess the persistence of renal insufficiency after drug cessation." (PMID 34461843, 2021).
chronic granulomatous disease (22 papers, 2011 to 2025). Chronic granulomatous disease (CGD) is a rare primary immunodeficiency, mainly affecting phagocytes, which is characterized by an increased susceptibility to severe and recurrent bacterial and fungal infections, along with the development of granulomas. "Neutrophils with reduced ROS production, such as those from patients with chronic granulomatous disease or myeloperoxidase (MPO) deficiency, produce fewer NETs in response to inflammatory stimuli." (PMID 22912772, 2012). "Neutrophils isolated from patients with chronic granulomatous disease (CGD) or from donors who are deficient in MPO function have impaired localization of NE into the nucleus, following stimulation with either Candida albicans or phorbol 12-myristate 13-acetate (PMA)." (PMID 38474270, 2024). "Myeloperoxidase mutants lead to impaired ROS production, making the host susceptible to infection, and thus, both MPO and NADPH oxidase mutants are unable to eradicate fungal threats like chronic granulomatous disease (CGD) and IA." (PMID 34490039, 2021). "In line with this we found that MSU-triggered NET formation was independent of ROS production and proceeded normally in neutrophils from patients with dysfunctional respiratory burst (chronic granulomatous disease (CGD) and complete myeloperoxidase (MPO) deficiency)." (PMID 32466527, 2020). "Additionally, neutrophils from chronic granulomatous disease patients, carrying mutations in the NADPH oxidase complex or a MPO-deficient patient were examined." (PMID 28574339, 2017). "Patients with chronic granulomatous disease (CGD), who are deficient in NADPH oxidase activity, and individuals who are completely deficient in myeloperoxidase (ΔMPO) are susceptible to opportunistic infections, particularly to fungal pathogens." (PMID 25066128, 2014). "In chronic granulomatous disease (CGD) patients who had damaged NADPH oxidase function affecting the production of hydrogen peroxide, it was difficult for the reaction substrate of MPO to form NETs." (PMID 38275657, 2024). "A subsequent study compared the response of MPO-deficient neutrophils and neutrophils from patients with the chronic granulomatous disease (CGD) lacking NADPH oxidase to C. albicans, showing that the postphagocytic oxidative burst was completely disrupted CGD." (PMID 33916434, 2021). "by phagocytes since invasive disease has been documented in patients with chronic granulomatous disease (CGD), and because defective myeloperoxidase-dependent oxidative systems were found to increase susceptibility to experimental T. asahii infection." (PMID 28439501, 2017). "The patient did demonstrate an elevated absolute neutrophil count (ANC) of 19,680 cells/microliter on dihydrorhodamine (DHR) flow cytometric blood tests, but other values were WNL, and the results were not consistent with chronic granulomatous disease (CGD) or myeloperoxidase deficiency." (PMID 41541964, 2025). "Such an hypothesis gains support from published data; cells from mice deficient in MPO produce increased levels of cytokines including TNFα, as do cells that cannot produce NADPH-oxidase-derived ROS, isolated from patients suffering from chronic granulomatous diseases (CGD)." (PMID 37954595, 2023).